HMGB1 (high mobility group box 1)
Diseases named in the same sentence as HMGB1 in open-access papers (continued):
Sharing a sentence is not in itself a finding about the gene and the disease.
tumor (continued). "Some studies have shown that HMGB1 can inhibit tumor cell growth by interacting with TLR4 and triggering the production of immunosuppressive proteins." (PMID 40969278, 2025). "The study emphasized that HMGB1 not only serves as a biomarker for disease progression but also actively participates in modulating the tumor microenvironment." (PMID 41009692, 2025). "Mechanistically, tumor cells suppress the transcriptional repressor Gfi-1, which normally inhibits HMGB1 expression, thereby amplifying HMGB1-driven autophagy and concurrently elevating multiple efflux transporters." (PMID 41465435, 2025). "HMGB1 has complex roles: it enhances radioresistance, promotes metastasis and proliferation, yet also exhibits tumor suppressive effects." (PMID 41463178, 2025). "Herein, the HMGB1 expression was significantly increased in the tumor area when compared with that in its adjacent counterpart." (PMID 40331953, 2025). "During OV-induced tumor cell lysis, the release of DAMPs (e.g., HMGB1, adenosine triphosphate [ATP]) and TAAs effectively promotes DC maturation and antigen presentation." (PMID 41314288, 2025). "For instance, elevated HMGB1 expression levels are often observed in chemotherapy‐resistant tumor cells and are positively correlated with enhanced autophagic activity." (PMID 41354099, 2025). "Firstly, the tumor-type specificity of HMGB1-mediated resistance mechanisms remains inadequately elucidated, particularly within the diverse immunological and metabolic microenvironments." (PMID 40969278, 2025). "In the cytoplasm, lactylated HMGB1 regulates endothelial permeability, inflammation surrounding tumor cells, and stromal remodeling in the TME, thereby influencing the characteristics of the TME." (PMID 40584966, 2025). "In terms of resistance, both the nuclear and cytoplasmic HMGB1 promote autophagy and inhibit tumor cell apoptosis to induce chemotherapy resistance." (PMID 40495163, 2025). "The dualistic role of HMGB1 in tumor progression and inflammatory responses exemplifies the complexity inherent in cellular physiological and pathological mechanisms." (PMID 41354099, 2025). "Platelets become locally activated through the interaction of podoplanin with C-type lectin-like immune receptor 2 (CLEC-2) on tumor cells, as well as high-mobility group box 1 (HMGB1) with TLR4." (PMID 40723273, 2025). "Recombinant HMGB1 obviously restored tumor formation, tumor number, and tumor load in Gsdmc2–4−/− mice." (PMID 40213993, 2025). "Immunofluorescence staining of ICD markers, including CRT and HMGB1, was carried out in tumor tissues." (PMID 40854883, 2025). "Recent work further refined this model, showing that HMGB1 released by mesothelial cells initiates carcinogenesis, while macrophage-derived HMGB1 sustains tumor growth and invasion at later stages." (PMID 40559922, 2025). "Astrocytic endfeet surrounding the co-opted vessels respond to tumor-derived HMGB1, S100B, and extracellular ATP with a stimulation of NFκB-TLR4 and P2X7 signaling in astrocytes." (PMID 41463339, 2025). "The sequestration of HMGB1 prevents its binding with tumor nucleic acids, inhibiting DNA sensing and DC activation, thereby promoting tumor escape." (PMID 41176596, 2025). "Previous studies have demonstrated that HMGB1 plays a pivotal role in tumor angiogenesis across multiple cancer types." (PMID 41354099, 2025). "Neutrophils also contribute to GBM growth via neutrophil extracellular trap (NET) formation through HMGB1/RAGE/IL-8 signaling, while LC3-associated phagocytosis can induce tumor cell ferroptosis and necroptosis." (PMID 40948940, 2025). "Through the modulation of autophagy, enhancement of DNA repair, immune evasion, and remodeling of the tumor microenvironment, HMGB1 profoundly influences treatment outcomes." (PMID 40969278, 2025). "Regarding immune modulation, APSMR induced pronounced ICD, characterized by the externalization of CRT on tumor cell surfaces and the release of HMGB1 and ATP." (PMID 40525676, 2025).
tumor (continued). "TANs demonstrate temporal phenotypic plasticity, comprising early-stage N1 phenotype, which induces tumor cell ferroptosis and necroptosis, and late-stage N2 phenotype, which facilitates tumor progression through the HMGB1/RAGE/IL-8 signaling axis." (PMID 40948940, 2025). "Dead tumor cells released HMGB1 and CRT to promote dendritic cell maturation and subsequent T cell activation, triggering anti-tumor immunity." (PMID 39776799, 2025). "In this process, tumor cells will release DAMPs (such as HMGB1, ATP, CRT, etc.), which can be used as signals of “eat me” and “find me” to attract and activate DCs and other immune cells, thus triggering adaptive immune response." (PMID 40535125, 2025). "Critically, as illustrated in the figure, dying tumor cells undergoing apoptosis and pyroptosis release damage-associated molecular patterns (DAMPs) such as CRT, ATP, and HMGB1, which serve as “danger signals” that recruit and activate dendritic cells (DCs)." (PMID 40949866, 2025). "Increased HMGB1 levels in the RO group at week 16 suggest that this compound actively influenced the tumor microenvironment." (PMID 40943044, 2025). "The extracellular functions of HMGB1 exhibit dual consequences that critically determine the therapeutic outcome and immune microenvironment activities, driving both anti-tumor and pro-tumor immune response, depending on the context." (PMID 41465435, 2025). "Components of the pre-metastatic niche also accelerate the generation of NETs, with IL-8, HMGB1 and G-CSF derived from tumor cells being key initiating factors." (PMID 40391215, 2025). "Studies have found that aging PC cells can alter the tumor microenvironment by releasing high mobility group box 1 (HMGB1), one of the specific ligands of TLR-4." (PMID 40404908, 2025). "The extracellular HMGB1 activates TLR4 on tumor cells to induce EMT‐related genes (e.g., Twist, MMP2, MMP9), enhancing migration/invasion." (PMID 41354099, 2025). "Flow cytometry analysis of immune infiltration in tumor tissues revealed that HMGB1 knockdown abrogated the increase in the proportion of M1 macrophages and decrease in the proportion of M2 macrophages induced by ADVNE and ADVPPE." (PMID 40082916, 2025). "Astrocytes also respond to melanoma by activating NF-κB–TLR4 and P2X7 pathways when exposed to tumor-derived HMGB1, S100B, and ATP." (PMID 41463339, 2025). "We observed three canonical hallmarks of ICD: translocation of CRT to the tumor cell surface, ATP release, and HMGB1 secretion." (PMID 41304785, 2025). "The topoisomerase II inhibitor teniposide mediates the cGAS-STING axis and induces tumor immunogenicity by inducing the release of high-mobility group box 1 (HMGB1) and type I IFN signaling in tumor cells." (PMID 40643531, 2025). "HMGB1 plays a crucial role in initiating neutrophil pro-tumor activation, interacting with TLR4 to activate the TNF-β pathway and induce autophagy and pro-tumor activation of neutrophils via HMGB1/TLR4/NF-κB signaling." (PMID 40108630, 2025). "HMGB1 generated from tumor tissues activates CD8+ T cells against glioblastoma and initiates TLR2 signaling." (PMID 40727443, 2025). "ELISA tests on serum confirmed that tumor-bearing mice have higher blood HMGB1 concentrations compared to naïve mice." (PMID 40007542, 2025). "On the other hand, the anti-tumor properties of HMGB1 are primarily manifested through its capacity to augment the immune system’s recognition and targeting efficiency against malignant cells." (PMID 40969278, 2025). "With extended irradiation time, the surface exposure of calreticulin (CRT) on tumor cells and the release of high mobility group box-1 protein (HMGB1) into the culture supernatant were significantly increased." (PMID 41383334, 2025). "Secretory autophagy, particularly involving HMGB1, plays a key role in mediating the crosstalk between tumor cells and clinical treatments, affecting tumor sensitivity to therapeutic agents such as TMZ." (PMID 39893499, 2025).
tumor (continued). "They found that necroptotic cancer cells released various danger signals and pro-inflammatory molecules, such as high-mobility group box 1 (HMGB1) and ATP, which promoted the activation of dendritic cells and the recruitment of immune cells to the tumor site." (PMID 40064873, 2025). "HMGB1 was significantly overexpressed in tumor tissues, highlighted by the expression increment in patients with M1 advanced metastasis tumors with immunoreactivity scores 2.61 and 6.50 for adjacent and tumor tissues, respectively (p-values = 0.0035)." (PMID 40331953, 2025). "HMGB1‐mediated RAGE signaling drives M2 macrophage polarization in the tumor microenvironment, amplifying immunosuppressive activity that fuels tumor growth and progression." (PMID 41354099, 2025). "The persistent activation of RAGE by HMGB1 released from necrotic tumor cells further reinforces resistance by inducing pro-survival autophagy and inhibiting apoptotic pathways, creating a feedback loop that maintains the resistant phenotype." (PMID 41465435, 2025). "HMGB1 produced by the pyroptotic tumor cells can promote the APC activation and antigen presentation." (PMID 40064873, 2025). "This is followed by immunostimulatory DAMPs secreted by dying tumor cells such as passive release of HMGB1, calreticulin surface translocation, and ATP release that act on TLRs of DCs to promote their maturation." (PMID 41375050, 2025). "ICD promotes the exposure of calreticulin to the surface of tumor cells through endoplasmic reticulum stress characterized by reactive oxygen species accumulation, and promotes the release of HMGB1 and other DAMPs (including ATP)." (PMID 41425703, 2025). "The released HMGB1 recruits nucleic acids from dead tumor cells into the endosome of DCs, initiating innate nucleic acid sensing." (PMID 41176596, 2025). "Studies have shown that extracellular HMGB1 protein, released via secretory autophagy, acts as a key regulator of crosstalk between tumor cells and the immune microenvironment." (PMID 39893499, 2025). "Compared with those in the sh-NC group, the tumors in the HMGB1 depletion and IR groups grew even slower in terms of tumor volume and weight." (PMID 41164196, 2025). "In summary, we demonstrated that HMGB1 released from tumor cells treated with the recombinant adenoviruses ADVNE or ADVPPE binds to the TLR4 receptor on macrophages, activating the MyD88-NFκB-NLRP3 (ASC) pathway and inducing M1 macrophage polarization." (PMID 40082916, 2025). "The expression of calreticulin (CRT) and high mobility group box-1 (HMGB1), which are tumor immunity activators, increased with 5-ALA alone in 3% O2 environment but was suppressed by X-ray irradiation across all environments." (PMID 41463178, 2025). "The release of HMGB1 enhances the immunogenicity of apoptotic cells, and when HMGB1 is secreted by dying tumor cells, it augments tumor-specific immune responses through toll-like receptor 4 (TLR4) signaling." (PMID 39893499, 2025). "For example, NE and high-mobility group box 1 protein (HMGB1) released during NETosis can drive tumor cell cycling and growth." (PMID 41516032, 2025). "In conclusion, autophagy is a key driver of HMGB1 secretion, establishing a powerful bidirectional communication circuit within the tumor and its microenvironment." (PMID 41465435, 2025). "The exposure of CRT on the surface of tumor cells provides a signal for immune cells to phagocytose the dying cells, while ATP and HMGB1 further amplify the immune response, enhancing dendritic cell maturation and the activation of CTLs." (PMID 40299564, 2025). "Considering that the nuclear protein HMGB1 is released in response to diverse stimuli, including lactate, we focused on the expression level of HMGB1 within tumor cells after co-culture with SCs." (PMID 40148311, 2025).
tumor (continued). "To investigate the role of HMGB1 in SC dedifferentiation and its impact on tumor progression, we introduced glycyrrhizin (1 nM) to inhibit HMGB1 expression in subsequent protein immunoblotting and IF experiments." (PMID 40148311, 2025). "In the tumor microenvironment, HMGB1 creates a permissive microenvironment for angiogenesis by modulating inflammatory responses and extracellular matrix (ECM) dynamics." (PMID 41354099, 2025). "Another context where HMGB1-mediated autophagy exhibits adaptive functions is under the oxidative stress, a common feature of tumor physiology, arising from oncogenic metabolism, hypoxia, and therapeutic intervenions." (PMID 41465435, 2025). "The small molecule ethyl pyruvate (EP) exerts broad anti-tumor effects primarily by inhibiting the nucleocytoplasmic translocation and release of HMGB1." (PMID 41465435, 2025). "For example, calreticulin interacts with a variety of immune cell receptors such as CD91 that can stimulate phagocytosis of immune cells against tumor cells, while HMGB1 release can play an important role in the activation of antigen-presenting cells." (PMID 40356923, 2025). "During the process, dying tumor cells release damage-associated molecular patterns (DAMPs, such as ATP, CRT and HMGB-1), as well as tumor-associated antigens (TAAs)." (PMID 41304791, 2025). "HMGB1, released by tumor cells upon forming complexes with genomic DNA, activates the cGAS‐STING pathway in dendritic cells to enhance anti‐tumor immunity." (PMID 41354099, 2025). "Radiation also induces the release of danger signals, such as HMGB1, ATP, and translocation of calreticulin to the tumor cell surface." (PMID 39941843, 2025). "This form activates antitumor immune responses by promoting the exposure and release of damage‐associated molecular patterns (DAMPs), such as calreticulin, ATP, and HMGB1, which stimulate dendritic cell maturation and tumor‐specific T lymphocyte responses." (PMID 40916083, 2025). "The enhanced response correlated with increased activation of CD8+ T cells in tumor-draining lymph nodes and elevated serum HMGB-1 levels." (PMID 40568078, 2025). "TIM-3 is expressed in a variety of immune cells and tumor cells, and regulates immune responses and inflammatory pathways through interactions with its ligands (e.g. Gal-9, HMGB1, CEACAM1 and PtdSer)." (PMID 40904469, 2025). "Some studies have demonstrated that tumor cells expressing advanced glycation end-product receptors bind HMGB1, activating nuclear factor kappa-B (NF-κB) signaling and inducing interleukin-8 (IL-8) release." (PMID 40655142, 2025). "Herein, we found that HMGB1 was overexpressed in tumor tissues when compared with that in nearby normal tissues." (PMID 40331953, 2025). "Nucleus and cytoplasmic HMGB1 promotes autophagy and inhibits apoptosis in tumor cells to induce chemoresistance." (PMID 41296391, 2025). "HMGB1 also reportedly enhances anti-tumor immune response by stimulating mature DC tumor antigen procesing." (PMID 39853458, 2025). "Across multiple tumor types, HMGB1 modulates both intrinsic and extrinsic apoptotic pathways, thereby promoting resistance to chemotherapy, radiotherapy, and targeted agents." (PMID 41465435, 2025). "In contrast, exposure to dying tumor cells or immunogenic stimuli (e.g., DAMPs like HMGB1 and calreticulin) can transiently enhance phagocytosis." (PMID 40724825, 2025). "ICD is a drug-induced apoptotic process that is accompanied by the expression of calreticulin on the surfaces of dying tumor cells and the release of high-mobility group box 1 (HMGB-1) and ATP." (PMID 40142031, 2025). "In recent years, HMGB1 has been shown to promote tumor cell metastasis and progression through processes like EMT and angiogenesis." (PMID 39849606, 2025). "This compound enhances the immunogenicity of tumor cell death by shifting the cell death pathway from apoptosis to necroptosis, leading to increased release of DAMPs, such as HMGB1." (PMID 41235238, 2025).
tumor (continued). "HMGB1 participates in the DNA damage repair process, thereby facilitating the repair of chemotherapy‐induced DNA damage in tumor cells." (PMID 41354099, 2025). "HMGB1 was only increased when tumor spheres were treated with poly (A:U) and when adherent cells were treated with poly (I:C)." (PMID 40647457, 2025). "The nanocarrier targeting tumor cell‐intrinsic FABP5 resulted in the downregulation of HMGB1 expression, thereby amplifying the ICD induced by RFA." (PMID 40956367, 2025). "These DAMPs, including CRT, ATP, and HMGB1, collectively drive a robust immune response, ensuring that the dying tumor cells are recognized and attacked by the immune system." (PMID 40299564, 2025). "Extracellularly, HMGB1 enhances chemotherapeutic effects by shifting tumor cells from apoptosis to senescence." (PMID 41296391, 2025). "The release of tumor antigens and exposure to danger signals such as high mobility group box 1 (HMGB1), calreticulin, heat shock protein 70 (HSP70), and adenosine triphosphate (ATP), enhance DC recruitment and T cell priming." (PMID 41176596, 2025). "Tumor cell-derived HMGB1 has been shown to induce regulatory T cells (Tregs) to produce IL-10, which in turn suppresses CD8+T cell-dependent antitumor immunity." (PMID 40169575, 2025). "The positive impact on anti-tumor immunity suggests that ferroptosis-derived ATP and HMGB-1 activate bone marrow-derived DCs, which aligns with our results." (PMID 39842944, 2025). "Upon analyzing HMGB1 localization, we found that HMGB1 was strongly expressed in the enlarged tumor group (T4) and in tumors with perforation in the visceral peritoneum group." (PMID 40331953, 2025). "Over recent years, several comprehensive reviews have examined the multifunctional roles of HMGB1 in cancer, including its immunological functions, its impact on the tumor microenvironment, and its contributions to inflammation-driven tumor progression." (PMID 41465435, 2025). "HMGB1, a damage‐associated molecular pattern (DAMP) molecule, has been shown to promote tumor metastasis by modulating the tumor microenvironment and facilitating angiogenesis." (PMID 41479846, 2025). "Under specific conditions, HMGB1 release during pyroptosis can paradoxically fuel tumor progression and confer therapy resistance." (PMID 41465435, 2025). "HMGB1 is released extracellularly from tumor cells following apoptosis and necrosis induced by radiation therapy, chemotherapy, and other treatments." (PMID 41463178, 2025). "This complex duality explains why HMGB1 can both potentiate ferroptosis-induced tumor clearance and, under different conditions, maintain resistance by stabilizing antioxidant defenses or shaping an immune-evasive microenvironment." (PMID 41465435, 2025). "Semiquantitative analysis revealed that the reduction in HMGB1 signal efficiency in tumor slices treated with iMWA combined with DA‐COD‐OD‐HCS (group III) was the greatest, at only 18.6%, compared with that in group I." (PMID 39664002, 2025). "The interaction betweenTIM-3 and the HMGB-1 mediates the suppression of tumor-infiltrating DCs by competing with nucleic acid for binding to HMGB-1." (PMID 40332725, 2025). "One study reported the association of a composite model including cytoplasmic expression of high mobility group box protein 1 (cyto-HMGB1) and PD-1+ tumour infiltrating lymphocytes on overall survival." (PMID 41487587, 2025). "Our findings demonstrated that HMGB1 overexpression led to increased PD-L1 expression and larger tumor size compared to controls, whereas HMGB1 knockdown resulted in decreased PD-L1 levels and smaller tumors." (PMID 40389855, 2025). "The tumor volume and weight appeared to increase in HMGB1-overexpressing 4T1 cells (H-Ctrl) compared to that in empty vector-transfected (E/V-Ctrl) cells, while treatment with ICM (H-ICM) or Stattic (H-Stattic) reduced the increases." (PMID 40389855, 2025).